DHX8 (DEAH-box helicase 8)
Description:
Involved in pre-mRNA splicing as component of the spliceosome. Facilitates nuclear export of spliced mRNA by releasing the RNA from the spliceosome.
Synonyms: DDX8; HRH1; Prp22; PRPF22; Dhr2
Tractability: Small molecule: a structure with a bound ligand is known. PROTAC: UniProt records ubiquitination sites on it; ubiquitination databases record sites on it; its protein half-life has been measured.
Target class: Enzyme; Hydrolase
Gene: Protein-coding gene on chromosome 17 (43,483,865 to 43,610,338, forward strand). Ensembl gene ENSG00000067596.
Subcellular location: Nucleus
Subcellular location (Human Protein Atlas): Nucleoplasm; Nuclear bodies
Pathways (Reactome):
Metabolism of RNA: mRNA Splicing - Major Pathway
Gene Ontology:
Molecular function: identical protein binding; protein binding; RNA binding; ATP hydrolysis activity; ATP-dependent activity, acting on RNA; RNA helicase activity; ATP binding; nucleic acid binding
Biological process: mRNA splicing, via spliceosome; RNA processing; RNA splicing
Cellular component: catalytic step 2 spliceosome; nucleoplasm; nucleus; post-spliceosomal complex; spliceosomal complex; U2-type catalytic step 1 spliceosome; U2-type catalytic step 2 spliceosome; ribonucleoprotein complex
Genetic constraint (gnomAD): Loss-of-function variants: 60 observed, 134.38 expected, observed/expected ratio (o/e) 0.45, 90% interval 0.36 to 0.55. The upper end of that interval is the gene's LOEUF score, 0.55, which puts it in group 2 of 6, group 1 being the genes least tolerant of losing a copy. Missense variants: 816 observed, 1,557.3 expected, observed/expected ratio (o/e) 0.52, 90% interval 0.49 to 0.56. Synonymous variants: 514 observed, 561.36 expected, observed/expected ratio (o/e) 0.92, 90% interval 0.85 to 0.99.
Homologues: Orthologues: chimpanzee DHX8 (100% identical), macaque DHX8 (99% identical), rabbit DHX8 (99% identical), rat Dhx8 (99% identical), mouse Dhx8 (99% identical), pig DHX8 (98% identical), guinea pig DHX8 (97% identical), dog DHX8 (91% identical), zebrafish dhx8 (90% identical), tropical clawed frog dhx8 (89% identical), Drosophila melanogaster pea (70% identical), Caenorhabditis elegans mog-5 (60% identical). Paralogues in human: DHX38 (37% identical), DHX16 (37% identical), DHX15 (31% identical), DHX35 (26% identical), DHX33 (25% identical), DHX37 (24% identical), DHX40 (23% identical), DHX34 (21% identical), DHX57 (21% identical), DHX29 (20% identical), DHX36 (19% identical), DHX9 (19% identical), and 6 more.
Diseases named in the same sentence as DHX8 in open-access papers:
DHX8 is named in the same sentence as 9 diseases in open-access papers, as found by Europe PMC text mining. Sharing a sentence is not in itself a finding about the gene and the disease. The quoted sentences say what the papers report.
Autoimmunity (1 paper, 2025). The occurrence of an immune reaction against the organism's own cells or tissues. "Two de novo variants occurring in genes not previously linked to SLE or autoimmunity, DHX8 and ACTR5, enhanced type I IFN signaling." (PMID 40386946, 2025).
Hypertension (1 paper, 2014). The presence of chronic increased pressure in the systemic arterial system. "TRAT1 and DHX8 have little exposure in the literature related to hypertension or related outcomes." (PMID 25519321, 2014).
melanoma (1 paper, 2024). A malignant, usually aggressive tumor composed of atypical, neoplastic melanocytes. "Certainly, the associations between DHX8 and immunomodulation in melanoma requires further validation." (PMID 38474285, 2024).
Spinocerebellar ataxia type 3 (1 paper, 2025). "To further validate the generality of DHX8 function, we established and used MEF and N2a cell lines stably expressing full-length ATXN3–Q79, a polyQ disease-associated protein encoded by ATXN3, mutations of which cause spinocerebellar ataxia type 3." (PMID 40842239, 2025).
cancer (3 papers, 2021 to 2026). A tumor composed of atypical neoplastic, often pleomorphic cells that invade other tissues. "Importantly, DHX8 loss significantly alters RNA processing of an HSF1-regulated cancer-associated gene signature linked to poor clinical outcomes, as well as additional oncogenic and stress-response pathways." (PMID 41837178, 2026). "We investigated the role of DHX8 in regulating HSF1 within the broader context of DHX8 function in cancer cells." (PMID 41837178, 2026). "We also find that DHX8 silencing triggers apoptosis more effectively in human cancer cells than in non-tumorigenic cells." (PMID 41837178, 2026). "DHX8, EIF3G, RBM22, U2AF1 UPF1 and YBX-1 are also candidates therapeutic targets for cancer therapy because the tumor cell progression was strongly inhibited by the downregulation of these RBPs in cancer cells, including HCT116, SUIT2 and OE33 cells, but not in non-cancerous cells." (PMID 34202873, 2021). "Our findings identify DHX8 as a critical regulator of stress-adaptive gene expression, highlighting its promise as a therapeutic target not only to disrupt HSF1-dependent transcriptional programs but also having broader effects in cancer cells under oncogenic stress." (PMID 41837178, 2026).
tumor (3 papers, 2021 to 2026). "Similarly, the RNA modification-related genes DHX35, DHX8, ENY2, and FTSJ1 also upregulated in most tumor tissues." (PMID 40041484, 2025).
DHX8 also shares sentences with these, for which no sentence is quoted: esophageal cancer (1 paper); pancreatic cancer (1); psoriasis (1).